CXCR3 (C-X-C motif chemokine receptor 3)
Diseases named in the same sentence as CXCR3 in open-access papers (continued):
Sharing a sentence is not in itself a finding about the gene and the disease.
tumor (continued). "Together, these data suggest a selective exclusion of CXCR3+ conventional T cells from the tumor-associated mucosa, with a concomitant recruitment of CCR4+ Treg and conventional CD4+ T cells." (PMID 22319577, 2012). "The frequencies of cells expressing α4β7 and the Th1 associated chemokine receptor CXCR3 were significantly decreased among CD4+ T cells in the tumor, while frequencies of CD4+CCR4+ lymphocytes were significantly increased." (PMID 22319577, 2012). "If true, we would expect that patients with improved survival would have high tumour islet expression of chemokine receptors known to be associated with favourable prognosis in cancer such as CXCR3 and CCR1." (PMID 20429924, 2010). "In addition, IP‐10 and CXCR3 are associated with anti‐tumor immunity in HCC patients and represent a potential target for the treatment of HCC." (PMID 40145607, 2025). "The binding of PMN-MDSCs in state 1 to CXCR3 was associated with cell recruitment and immune modulation in the early tumour microenvironment, whereas in other states, the involvement of CXCR4 was linked to cell migration, survival, and other immune evasion mechanisms." (PMID 40429821, 2025). "Given that Cxcl9 and Cxcl10 share the same receptor CXCR3, we hypothesized that Sin3B loss recruited CD8+ T cells into the tumor milieu predominantly through the CXCL9/10‐CXCR3 axis." (PMID 39316363, 2024). "In addition to the quite complex biological behavior of CXCR3 and its ligands in tumor immunity, diverse CXCR3 splice variants exist, and they can be differently expressed in different cell types." (PMID 39596815, 2024). "MPM is strongly responsive to synthetic activators of cGAS/STING pathway that increase the production of CXCR3 in tumor cells and cancer-associated fibroblasts, resulting in the recruitment and activation of NK cells and mesothelin-targeted chimeric antigen receptor (CAR)-NK cells." (PMID 39709435, 2024). "Our study suggests a tumor load-dependent inflammatory circuit in MM with the release of CXCL10 from myeloid cells causing the migration of CXCR3 + inflammatory T cells from the periphery to the BM, in line with previous reports in the context of cancer and vaccinations." (PMID 39613747, 2024). "The CXCR3 axis is implicated as a possible driver of malignancy in HPVOPC via tumor growth stimulation, though caution is warranted as inhibition of this axis may also adversely impact immunosurveillance." (PMID 37686653, 2023). "By contrast, CD4+ Th cells from CAR T-vax-treated mice upregulated genes associated with Th1 function (Ifng, Cxcr3) and self-renewal (Slamf6, Tcf7), suggesting that the vaccine may also promote anti-tumor phenotypes among CD4+ TILs." (PMID 37413990, 2023). "PD-L1 and CXCR3 expressions were associated with tumor progression and a worse prognosis." (PMID 36726488, 2023). "Interestingly, blocking only CXCR3 led to a loss of tumor control through this combination therapy, underpinning the importance of Batf3 DCs and CXCR3 ligands for the recruitment of CTLs and tumor killing." (PMID 35626062, 2022). "In addition to induction of Th1 and NK cells, CXCL10 has been associated with the recruitment of CXCR3(+) CD8(+) T cells to the tumor site." (PMID 35408440, 2022). "Hence, we analyzed the relationships between the signature and TIP-related genes, and the results showed that cold tumor genes such as CXCL2 and CCL20 and hot tumor genes such as CXCR3, CXCL11, and PDCD1 were upregulated in the high-risk group in both cohorts." (PMID 35938001, 2022). "In the urology study, Vollmer and his team found that in treating patients with muscle-invasive bladder cancer, the intratumoral CXCR3 chemokine system (ligands and receptor splice variants) was identified as a critical component for tumor eradication upon neoadjuvant chemotherapy." (PMID 36479091, 2022). "The suppressed anti-tumor effect of CXCR3 might be related to the deficiency of functional NK cells and IFN-γ." (PMID 36479091, 2022).
tumor (continued). "However, it has also been suggested that it promotes tumor proliferation and metastasis, possibly because the ligand exerts different effects on different CXCR3 variants." (PMID 36479091, 2022). "Our results indicated that CXCR3 was downregulated in tumor-associated macrophages." (PMID 36249427, 2022). "Because CXCR3 ligation promotes the anti-tumor effects of PD-1 blockade in mice, further study of the CXCR3 variants, their ligands, and competing receptors on immune and parenchymal cells in the kidney may yield novel insights." (PMID 33676416, 2021). "While at first glance this might seem contradictory, previous research has shown CXCR3 is associated with a tumor specific immune response, which could explain these findings." (PMID 34440489, 2021). "In addition, CXCL10 was predominantly expressed by tumor associated macrophages and its receptor CXCR3 was highly expressed in T cells at the single-cell level." (PMID 34276760, 2021). "Indeed, we demonstrated that the homing and efficacy of PTPN2‐deficient CAR T cells was reliant on tumours expressing STAT‐1‐driven CXCR3 chemokines." (PMID 31803974, 2020). "To explore whether the increased cell surface CXCR3 might contribute to the increased homing and anti‐tumour activity of PTPN2‐deficient CAR T cells, we sought to correct the increased CXCR3 expression." (PMID 31803974, 2020). "Moreover, CXCR3 and its ligands levels were related to patient’s prognosis, risk of metastasis and tumor growth." (PMID 33202536, 2020). "Activation of the CXCR1/CXCR2 pathway and the CXCR4/CXCR7 pathway is associated with tumor aggressiveness and poor prognosis; the CXCR3 and CXCR5 axes play a role in tumor suppression; and common variants encoding the CXC chemokine gene have also been studied as biomarkers of CRC." (PMID 32774427, 2020). "Indeed, we observed no improvement in the efficacy of IL-12/15/18-stimulated NK cells upon CXCR3 blockade in vivo that is consistent with the mild increase of tumor clearance mediated by Cxcr3 deficient IL-12/15/18-stimulated NK cells in the short term." (PMID 31699153, 2019). "CXCR3 signaling has been implicated in tumor progression with a model emerging that signaling through the CXCR3-A isoform imparts migration and thus dissemination for the mesenchymal cells, whereas in the non-aggressive epithelial cells the CXCR-B isoform would block motility." (PMID 31831069, 2019). "However, CXCR3 chemokines do not only cause a tumor-suppressive milieu per se, they also contribute to the effect of multiple current cancer therapeutics." (PMID 31482487, 2019). "quanTIseq analysis of 8000 tumor samples revealed that cytotoxic T cell infiltration is more strongly associated with the activation of the CXCR3/CXCL9 axis than with mutational load and that deconvolution-based cell scores have prognostic value in several solid cancers." (PMID 31126321, 2019). "The authors observed that FMT from responding patients but not from non-responding patients into GF mice caused tumor growth delay, accumulation of CXCR3+CD4+ T cells in the tumor microenvironment, and up-regulation of PD-L1 in splenic T cells after PD-1 blockade." (PMID 31533218, 2019). "Since the reduced NK cell localization and anti-tumor efficacy in MM can be reverted by CXCR3 deficiency in the short time frame (48 h), we wanted to demonstrate that CXCR3/ligand axes can be exploited in NK cell-based immunotherapy by showing a long-term effect of CXCR3 inhibition." (PMID 31699153, 2019). "In contrast to this tumor model, we have recently demonstrated that CXCR3 and associated chemokine ligands are important in attracting an effector T cell population to the hyperplastic ear skin of mice transgenic for the human papillomavirus (HPV16) E7 oncogene." (PMID 30320116, 2018).
tumor (continued). "CXCR3 expression on primary lesion tumor cells is positively associated with deleterious clinical parameters including thickening of primary lesions, absence of lymphocytic infiltration, and presence of distant metastases but, surprisingly, is not correlated with patient outcomes." (PMID 30420855, 2018). "Furthermore, high tumor expression of CXCR3 ligands together with high expression of CXCR3 on T cells are both associated with a favorable prognosis in melanoma." (PMID 30420855, 2018). "Then, we investigated if changes in CXCR3 mRNA profile could be associated to tumor development by comparing the expression of CXCR3A and CXCR3B in nMPTC with B-CLT." (PMID 29416784, 2018). "The balance of protein levels of CXCR3A and CXCR3B found in nMPTC suggest that similar levels for CXCR3 variant might have a role during malignant transformation or tumor growth." (PMID 29416784, 2018). "CXCR3 is associated with monocytic and lymphocytic infiltration of inflamed or tumor-bearing lung." (PMID 28358049, 2017). "However, determining the role of CXCR3 in tumorigenesis is complicated by the fact that many cells in the tumour microenvironment potentially express CXCR3 splice variants and their ligands." (PMID 27297979, 2016). "In addition, the coupling of CXCL9 with its receptor CXCR3, has anti-angiogenic properties through direct interaction with the endothelium, causing suppression of tumor growth due to the suppression of neovascularization." (PMID 24278236, 2013). "Tumor-associated CXCR3+ Treg were mostly Helios-positive, and T-bet+ Treg could be generated in vitro by culturing CD45RA+CCR7+ rTreg (mostly containing tTreg) under Th1-polarizing conditions, suggesting their derivation from committed tTreg." (PMID 23986759, 2013). "Thus, a treatment-naïve “hot” tumor with cytotoxic CXCR3+-associated T-cell infiltration and adaptive immune resistance may represent a PDAC subset with untapped potential for immunotherapy." (PMID 40696453, 2025). "Therefore, higher expression of CXCR3 on NK cells in patients with BC might be associated with the potency of NK cell infiltration to tumor site." (PMID 38652012, 2024). "Indeed, PD-1high CAR T cells express slightly elevated levels of chemokine receptor CXCR3, which may be associated with improved recruitment and retention to tumor sites." (PMID 37388744, 2023). "The data presented here verified that CXCR3 expression was positively associated with immune cell infiltration, suggesting the overexpression of CXCR3 could probably increase the infiltration of immune cells of all sorts into the tumor microenvironment." (PMID 35978426, 2022). "Therefore, before using CXCR3 variants as potential anti-tumor targets, a better understanding of the biology of CXCR3 variants is needed to clarify their exact signaling pathways and cellular responses in the TME to lay a solid foundation for precise or combination tumor treatment." (PMID 36479091, 2022). "In addition, murine Nrp1-deficient Tregs are associated with a profound tumor resistance due to Treg functional fragility with the acquisition of characteristic T-helper lineage markers (such as T-bet, CXCR3, IRF4 and RORγt), even if they retain their Foxp3 expression." (PMID 33924428, 2021). "In addition, the differential actions of CXCR3 isoforms and the immune evasion of tumor cells may be associated with these phenomena." (PMID 34501934, 2021). "We did observe loss of CXCR3 in tumor-infiltrating CD8+ T cells from both WT and ALK5ΔCD8 animals suggesting that exhaustion is occurring through TGFβ-independent mechanisms, and may provide an opportunity for synergy with immune therapies targeting exhaustion, such as immune checkpoint blockade." (PMID 32273499, 2020). "Interestingly, we observed loss of CXCR3 expression in tumor-infiltrating CD8+ T cells over time, with complete loss by day 21, which may reflect the development of exhaustion, as has been shown during chronic LCMV infection." (PMID 32273499, 2020).
tumor (continued). "The chemokine receptor CXCR3 has also been known for its indispensable role in tumor immune microenvironment, which could promote the migration, activation, and differentiation of some tumor-associated immune cells." (PMID 31240220, 2019). "In alignment with this hypothesis, in a preclinical model of spontaneous prostate cancer, tumor growth was significantly increased in CXCR3-deficient mice compared with controls, with a corresponding increase in tumor angiogenesis as measured by von Willebrand factor RNA expression." (PMID 30800123, 2019). "Furthermore, CXCR3 is associated with Th1/Tc1 polarization and anti-tumor functions." (PMID 30420855, 2018). "Moreover, CXCR3 expression levels in primary tumor were causatively involved in LNM." (PMID 29416784, 2018). "However, it remains uncertain whether loss of host CXCR3 impaired initial engraftment or long-term survival of disseminated tumor cells." (PMID 28358049, 2017). "CXCR3 blockade and inhibition of T cells egressing from draining lymph nodes abolished the systemic anti-tumor efficacy." (PMID 41818612, 2026). "The tumor suppression effects of CCL2 inhibitor (Pirfenidone) and CXCR3 inhibitor (AMG487) are validated in the orthotopic tumor model." (PMID 42295734, 2026). "The development of intratumoral bystander TRM cells required intrinsic TGFβ-signaling, and their efficient tumor entry was dependent on CXCR3 and CXCR6 expression." (PMID 41461987, 2026). "Our study demonstrated that CXCL10+ macrophages and the CXCR3+ T cells were critical mediators of the systemic anti-tumor immunity induced by cryoablation in advanced NSCLC." (PMID 41818612, 2026). "Genetic silencing of Cxcl10 in dormant cells or pharmacological blockade of CXCR3 in vivo led to early tumor onset and rapid growth in immunocompetent mice." (PMID 41617729, 2026). "Here we show that DOT cells acquire a specific chemokine receptor profile during expansion to support tumor infiltration, characterized by prominent CXCR3 expression." (PMID 42208977, 2026). "In various tumors, the CXCL10/CXCR3 axis has also been found to regulate the migration, differentiation, and activation of immune cells, thereby inhibiting tumor growth." (PMID 41399390, 2026). "Altogether, these data establish that the functional outcome of P1C4 therapy—tumor rejection versus immune-mediated toxicity—relies on the specific co-expression of CXCR3, CCR5, and CXCR6 on responding T cells." (PMID 41415437, 2025). "Co-expression of CCR5, CXCR6, and CXCR3 provides a functional ‘code’ that separates T-cell-mediated anti-tumor efficacy from off-target toxicity, enabling the selection of superior cells for safer and more effective cancer immunotherapies." (PMID 41415437, 2025). "Blocking CXCR3 impairs the efficacy of PD-1 blockade, whereas enhancing its expression promotes T-cell infiltration and tumour suppression." (PMID 40361472, 2025). "Mechanistically, Akkermansia induced IL-12 production, which promoted the infiltration of CCR9+CXCR3+CD4+ T lymphocytes into the tumor microenvironment, thereby rescuing ICI responsiveness." (PMID 41030553, 2025). "In reverse, TAMCs-derived CXCL10 reversely promoted tumor epithelial-mesenchymal transition and induced immunosuppressive tumor microenvironment by recruiting CXCR3+ Tregs." (PMID 39965084, 2025). "Two weeks after tumor induction, young mice treated with CXCR3 blockade developed larger tumors and exhibited reduced tumor-associated T cell infiltration." (PMID 41332581, 2025). "Autocrine signaling of the Cxcl10/Cxcr3 axis was shown to promote tumor cell growth, motility, and metastasis." (PMID 40486289, 2025). "This chemokine acts as a beacon, recruiting CXCR3-expressing CD8+ T cells from the host into the tumor." (PMID 41463372, 2025). "ScRNA-seq analysis revealed elevated expression of Cxcr3, consistent with enhanced tumor-homing capacity, alongside production of Cxcl10, suggesting a chemoattractant role." (PMID 40229241, 2025).
tumor (continued). "DGE analysis revealed that liver Tregs, compared to tumor and PBMC Tregs, had higher expression of key genes linked to Treg recruitment and immune suppression (e.g., CXCR3, CCL3, CCL4, and CCL5)." (PMID 40848148, 2025). "CXCR3 also plays an important role in the accumulation and immune suppressive function of tumor-infiltrating Tregs." (PMID 41041322, 2025). "CXCL10 facilitates the recruitment of CXCR3+ - CTLs, NK cells and Th1 cells into the tumor microenvironment, where they play an essential role in the recognition and destruction of tumor cells." (PMID 40760734, 2025). "The role of CXCL10 and its receptor CXCR3 in tumorigenesis and tumor progression was complex and multifaceted." (PMID 40129528, 2025). "In the dual-knockdown (PRMT5 and CXCR3) model, while the tumor cells still have PRMT5 knockdown, the host’s T cells lack the CXCR3 receptor." (PMID 41463372, 2025). "Mechanistically, CXCL10 plays a key role by recruiting CXCR3+ CD8+ T cells to the tumor microenvironment, which in turn enhances IFN-γ production and sustains a Th1‐polarized immune response." (PMID 40760734, 2025). "Specifically, tumor-bearing mice were treated with DB together with control IgG, or neutralizing antibodies for CXCR3 (αCXCR3, 140 μg/mouse) every 4 days or CXCL9 (αCXCL9, 200 μg/mouse) every 3 days, starting 6 days after B16-OVA cell inoculation." (PMID 40867314, 2025). "As expected, CXCR3 is critical for T-cell trafficking into the tumor, TdLNs, and liver following P1C4 treatment." (PMID 41415437, 2025). "The anti-tumor effects of DB2313 were abolished by depleting macrophages with clodronate or inhibiting the CXCL9-CXCR3 chemokine axis using CXCL9- or CXCR3-neutralizing antibodies." (PMID 40867314, 2025). "CD8+ T-cells, Th1 cells, and NK cells are critical for anti-tumour immunity, often expressing CXCR3." (PMID 40361472, 2025). "As a representative species, Akkermansia muciniphila has been shown to restore the efficacy of PD-1 blockade in an interleukin-12-dependent manner by increasing the recruitment of CCR9+CXCR3+CD4+ T cells into the tumor microenvironment." (PMID 41304278, 2025). "For instance, Vδ2+ T cells primarily migrate through CCR5-mediated chemotaxis, whereas Vδ1+ T cells predominantly rely on CXCR1 and CXCR3, leading to differentiated tissue migration and tumor infiltration patterns." (PMID 40141420, 2025). "Next, T cells must transmigrate through the endothelial cells to penetrate into the tumor stroma, again under the direction of chemokine gradients including CXCR3 and CCR5." (PMID 41008910, 2025). "The ligands CXCL9, CXCL10, and CXCL11 all bind to CXCR3 and are primarily secreted by immune cells such as leukocytes and macrophages, as well as by dendritic cells, fibroblasts, and tumor cells." (PMID 40362215, 2025). "In a mouse model of bone metastasis, systemic treatment with a neutralizing anti-CXCL10 antibody significantly reduced the migration of CXCR3-expressing cancer cells to the bone and decreased overall tumor burden." (PMID 41516196, 2025). "It has been reported that exercise contributes to tumor management by enhancing CD8+ T cell infiltration via mediating the CXCR3 signaling and thus boosts the response to immune checkpoint blockade in BRCA." (PMID 39845707, 2025). "Compared to the control group, combination treatment significantly increased the expression of Ifng, Tnf, Gzmb, Cxcr3, Cxcl11 and Ccl19 in the tumor, suggesting a more inflammatory TME." (PMID 39816690, 2025). "As transformed tumor cells progressively lose CXCR3 expression, they become less responsive to epidermal chemotactic signals, contributing to loss of epidermotropism and dermal accumulation." (PMID 40861461, 2025). "CXCL9, CXCL10, and CXCL11 interact with CXCR3 on tumor cells, immune cells, and vascular endothelial cells, influencing tumor growth, immune cell activity, and blood vessel formation." (PMID 40362215, 2025).